MMP11 (matrix metallopeptidase 11)
Diseases named in the same sentence as MMP11 in open-access papers (continued):
Sharing a sentence is not in itself a finding about the gene and the disease.
breast carcinoma (continued). "Thus, in the present study we evaluated the relationship between MMP-11 expression by MICs, distant metastasis development, and a wide panel of inflammatory factors in breast carcinoma." (PMID 23145063, 2012). "To examine whether there was correlation between the expression of ALK4 and MMP11, we examined expression of these proteins in human breast carcinoma specimens." (PMID 23211491, 2012). "In accordance to our data, that clearly show a significant increase in the expression of MMP-11 mRNA, propeptide and peptide in breast cancer compared to normal breast tissue, the studies of Pacheco and Kossakowska reported the same expression pattern for this matrix metalloproteinase." (PMID 19531263, 2009). "Accordingly, it has been reported that several other MMPs and TIMPs may be overexpressed and/or related to clinical outcome in breast cancer, such as MMP-11 MT1-MMP (MMP-14) MMP-13, TIMP-1 or TIMP-2." (PMID 17848954, 2007). "Furthermore, this study demonstrated the correlation of high MMP-11 expression with low infiltrating CD8+ or CD4+ T cells using immunohistochemical analysis, suggesting that the reduced anti-tumor immune response by MMP-11 contributes to the promotion of breast cancer progression." (PMID 36741729, 2022). "However, despite the obvious association of MMP-11 expression in MICs with poor clinical outcomes in patients with breast cancer, the role and molecular mechanisms of stromal MMP-11 in breast cancer remain unclear." (PMID 36741729, 2022). "The present study aimed to assess whether MMP-11 is related to clinicopathological parameters and the survival of breast cancer patients based on data from patients seen at Hanyang University Guri Hospital (HUGH) and from the The Cancer Genome Atlas (TCGA) database." (PMID 34038440, 2021). "Importantly, we found that circ-MMP11 could be transferred by exosomes in breast cancer, suggesting the significance of circ-MMP11 in breast cancer cells." (PMID 34295807, 2021). "Interestingly, in a recent report by our team, we showed that the coculture of CAFs, and especially those derived from breast carcinomas showing MMP-11 expression by stromal MICs, significantly increased the invasive capability of tumor cells with the cell line MDA-MB-231." (PMID 33669393, 2021). "Moreover, we considered that the exposure of antigenicity by MMP-11 could be insufficient to recruit different antitumoral immune cells to the tumor site in breast cancer." (PMID 34038440, 2021). "Circ-MMP11 could be transferred by exosomes in breast cancer cells." (PMID 34295807, 2021). "Furthermore, several studies have shown that MMP11 is a potential biomarker gene in breast cancer, which may facilitate the diagnosis and prognosis of breast cancer." (PMID 34587931, 2021). "Therefore, pictilisib and AZ960 may contribute to an improved treatment strategy for resistance to chemotherapy in breast cancer with high MMP-11 expression." (PMID 34038440, 2021). "Additionally, to further validate the regulatory role of circ-MMP11 could be mediated by the miR-153-3p/ANLN axis in LR breast cancer cells, rescue assays were performed." (PMID 34295807, 2021). "Therefore, circ-MMP11 was chosen for in-depth investigations in breast cancer." (PMID 34295807, 2021). "In addition, we have shown that CAF from MMP11 positive tumor-infiltrating immune cells tumors may overexpress tumor progression factors and may show higher breast cancer cell invasion and angiogenesis." (PMID 33396463, 2020). "However, the clinical and functional significance of MMP11 in HR−/HER2+ breast cancer remains unclear." (PMID 28409241, 2017). "Based on our results, effective and targeted therapy for patients with different breast cancer subtypes can be designed and optimized for clinical application to more precisely identify and attack cancer cells by selectively inhibiting the expression of MMP11 or inducing the expression of HPSE2." (PMID 26084486, 2015).
breast carcinoma (continued). "Moreover, expression of MMP-11 or PDGF-C indicated poor prognosis of breast cancer." (PMID 26456994, 2015). "A strong convergence was also observed for breast cancer: all manuscript-listed genes, including SCARA5, ADAMTS5, MMP11 and CAVIN2, appeared in the outputs of SHAP or LIME." (PMID 40565055, 2025). "Only MMP11, MYBL2, SFRP1, and UBE2C identified in our study are also featured together as biomarkers in the PAM50 breast cancer 50 gene panel." (PMID 39596491, 2024). "MMP11, also referred to as stromelysin-3, is a member of the MMP family and was initially identified in breast cancer." (PMID 39239548, 2024). "Interestingly, our analysis revealed a direct correlation between a high MMP-11 immunohistochemical score and an elevated tumor nuclear grade—a connection also supported by earlier studies that included a whole range of clinical and molecular breast cancer subtypes." (PMID 38438841, 2024). "In breast cancer, miR-98 can inhibit angiogenesis and invasion, primarily by suppressing the expression of ALK4 and MMP11, emphasizing its potential utility in prognosis and treatment approaches." (PMID 38872210, 2024). "MAGEA1/3/12/13, MMP11/13, PRAC2, CSAG1, COL10/11A1 genes are overexpressed in breast cancer samples from patients with PP." (PMID 36675137, 2023). "The genes namely COL11A1, MMP11 and COL10A1 were found up-regulated and PCOLCE2, LAMA2, TMTC1, and TIMP4 were found down-regulated in breast cancer cell lines also." (PMID 37238942, 2023). "For this purpose, we crossed MMP11-GOF and LOF mice with animals expressing the Mouse Mammary Tumor Virus (MMTV)-polyomavirus Middle T-antigen (PyMT), a mouse model of breast cancer." (PMID 37445827, 2023). "In breast cancer, BMP2 can regulate EMT and stemness by upregulating CD44 and MMP11 via PI3K/AKT and Smad signalling pathways." (PMID 37333824, 2023). "The genes namely COL11A1, MMP11 and COL10A1 were found up regulated and PCOLCE2, LAMA2, TMTC1, ADAMTS5, TIMP4 and RSPO3 were found down regulated in breast cancer." (PMID 37238942, 2023). "In conclusion, our study identified nine key regulators, of which COL11A1, MMP11 and COL10A1 were up regulated and PCOLCE2, LAMA2, TMTC1, ADAMTS5, TIMP4 and RSPO3 were down regulated in breast cancer samples as compared to control samples." (PMID 37238942, 2023). "Among these key genes COL11A1, MMP11 and COL10A1 were highly expressed and PCOLCE2, LAMA2, TMTC1, ADAMTS5, TIMP4, and RSPO3 were having lower expression levels in breast cancer samples." (PMID 37238942, 2023). "The chemokine CCL2 secreted by MMP11-overexpressing macrophages activates the MAPK pathway, inducing phosphorylation of ERK1/2 and JNK and promotion of HER2+ breast cancer cell migration facilitated by the upregulation of MMP9." (PMID 36591235, 2022). "Circ-MMP11 and ANLN were highly expressed, and miR-153-3p was decreased in LR breast cancer tissues and cells." (PMID 34295807, 2021). "CircMMP11 is overexpressed in breast cancer to upregulate matrix metalloproteinase-11 (MMP-11) by sponging miR-1204 and thereby increase cancer cell metastasis and growth, suggesting the role of circMMP11 as an oncogenic circRNA in breast cancer." (PMID 34749774, 2021). "PTK7 expression in breast cancer was significantly positively correlated with COL1A1, FN1, WNT5B, MMP11, MMP14 and SDC1 in breast cancer." (PMID 34367983, 2021). "Matrix metalloproteinase 11 (MMP11), or stromelysin-3, was first identified in the stromal cells of breast carcinoma." (PMID 31940762, 2020). "In the present study, we have investigated MMP1 and MMP11 gene expression in PBMC because of their relationship with lymph node metastasis and hematogenous metastasis in breast cancer, respectively." (PMID 33396463, 2020). "Up-regulated expression of COL10A1, MMP11, CST1, GJB2, MMP1, MMP13, and CEACAM6; down-regulated expression of ADH1B, CIDEC, THRSP, GPD1, TIMP4, FABP4, and SCARA5 genes was common in breast cancers of the two populations." (PMID 31292488, 2019).
breast carcinoma (continued). "QPCR analysis confirmed the up-regulated expression of MMP1, MMP13, and MMP11 genes and down-regulated expression of ADAMTS1 and ADAMTS5 genes in breast cancers observed in the microarray experiments." (PMID 31292488, 2019). "We also examined the relationship between MMP11 and CD2 gene expression and prognosis of patients with HR−/HER2+ breast cancer using public dataset to confirm their clinical significance in other cohorts." (PMID 28409241, 2017). "Up-regulated genes, such as COL10A1, MMP11, NEK2, PAFAH1B3, KIF4A are highly related to breast cancer." (PMID 28245581, 2017). "Here, our findings demonstrate for the first time the prognostic significance of MMP11 and CD2 expression in HR−/HER2+ breast cancer and suggest that they are promising biomarkers or drug targets for this subtype of breast cancer." (PMID 28409241, 2017). "With regard to DFS, the expression of MMP11 and UBE2C were independent prognostic factors in HR−/HER2+ breast cancer." (PMID 28409241, 2017). "Taken together, serum levels of IL-33, sST2, VEGF, MMP-11, and PDGF-C were higher in breast cancer patients than in healthy volunteers." (PMID 26456994, 2015). "Expressions of MMP11 and HPSE2, 2 genes closely involved in ECM-mediated cancer cell migration and angiogenesis, were found to be significantly different in breast cancer samples compared with normal controls." (PMID 26084486, 2015). "MMP-11 and PDGF-C protein levels were remarkably higher in sera of breast cancer patients than in sera of healthy volunteers (MMP-11: 53.07 ± 2.63 ng/mL versus 8.16 ± 0.14 ng/mL, PDGF-C: 1023.00 ± 47.76 pg/mL versus 524.90 ± 15.01 pg/mL)." (PMID 26456994, 2015). "All the results above suggest that MMP11 and HPSE2 can be used as a promising biomarker gene set in breast cancer." (PMID 26084486, 2015). "Serum levels of vascular endothelial growth factor (VEGF), metalloproteinase-11 (MMP-11), and platelet-derived growth factor-C (PDGF-C) were also greater in breast cancer patients compared to healthy volunteers." (PMID 26456994, 2015). "The first is matrix metalloproteinase-11 (MMP11), which is related with distance metastasis, resistance to anoikis and poor outcomes in breast cancer." (PMID 26569312, 2015). "MMP-11 and MMP-14 immunohistochemistry was performed on serial sections of human breast cancer biopsies." (PMID 25081520, 2014). "The proposed role of miR-98 in decreasing MMP11 and ADAM-15 expression can explain the tumorigenic properties of breast cancer cells." (PMID 23211491, 2012). "Therefore, the aim of the present study was to evaluate the relationship between MMP-11 expression by intratumoral MICs, distant metastasis development, and a wide panel of biological parameters related to tumor progression and inflammation in breast carcinoma." (PMID 23145063, 2012). "The tissue levels of at least MMP-1, MMP-2, MMP-9, MMP-11, membrane type (MT) 1-MMP, tissue inhibitors of metalloproteinases (TIMP) 1 and TIMP-2 have been correlated with poor outcome of breast cancer patients." (PMID 19243594, 2009). "Similar significant differences between normal breast tissue and grade 2 breast cancer tissue concerning the mRNA levels were observed for MMP-9 (p = 0,0127), MMP-11 (p = 0,0007) and MMP-13 (p = 0,008)." (PMID 19531263, 2009). "Matrix metalloproteinase-1 was immunohistochemically detected in 88.3% of breast carcinomas, MMP-2 in 42%, MMP-7 in 87.4%, MMP-9 in 74%, MMP-11 in 89.3%, MMP-13 in 73.3%, MMP-14 in 90%, TIMP-1 in 95%, TIMP-2 in 87% and TIMP-3 in 82.3%." (PMID 17848954, 2007). "Scanning the signatures in these genomic assays against the ten features used in our ‘normal’ vs. ‘cancer’ model yielded: two genes in common with Prosigna (FOXA1, MMP11), one gene with OncotypeDX (MMP11), one gene with HER2DX (NEK2), and one gene with Breast Cancer Index (NEK2)." (PMID 41048341, 2025).
breast carcinoma (continued). "There is a number of scientific research for each of the top 10 mRNA genes, well-documenting their significance and association with cancerogenesis: ADAMTS5, TMEM220, ARHGAP20, MICU3; or precisely with breast cancer: COL10A1, MMP11, CAVIN2 (formerly known as SDPR), PLPP3, MME, and CD300LG." (PMID 40724805, 2025). "This overexpression increases monocyte recruitment and promotes the migration of HER2 + breast cancer cells through the CCL2/CCR2/MAPK pathway, underscoring the significant impact of TAM-derived MMP-11 on the progression and metastatic potential of breast cancer." (PMID 38713256, 2024). "The metastasis-related gene MMP11 and proliferation-related genes BIRC5, MYBL2, MKI67 (Ki67), AURKA (STK15), CCNB1, and ERBB2 (HER2) from the Oncotype DX gene set exhibit significant up-regulation in tumor samples of breast cancer (BRCA)." (PMID 38254834, 2024). "To note, the protein–protein interaction network of PIK3R1, IL1R1, MMP11, GOLM1, and VAV3 altogether connected by EGFR merits further work to understand the mechanism and develop an ideal treatment strategy for invasive small tumor-size breast cancers." (PMID 39190284, 2024). "Overexpression of MMP-11 in macrophages, but not in cancer cells, increase monocyte recruitment and migration of Her-2+ breast cancer cells via CCL2/CCR2/MAPK pathway." (PMID 36906534, 2023). "Due to their solid digesting function, the matrix metalloproteases MMP1, MMP11, MMP14, and MMP16 might confer invasiveness to breast cancer cells through the Zn2+-bound ZEB1." (PMID 36910659, 2023). "MMP11, also known as stromelysin-3, is a member of the MMPs family and was first expressed in non-malignant fibroblast-like cells in the vicinity of breast cancer cells." (PMID 36756152, 2023). "Importantly, increases in COL8A1, BGN, COL11A1, POSTN, MMP11 and SORCS2 and decreased LTBP4, PCOLCE2, LRRC17 and SDK1 have been identified in CAS and CAFs from human breast cancer and are consistently perturbed in stroma of canine and human mammary cancer." (PMID 37391533, 2023). "Interestingly, we found that one CAF population from PCa presented a higher expression of IL-6, FGF7, MMP2 and MMP11, with a lower expression of FGF10 and IL-17RB than normal prostatic fibroblasts, which was consistent with those found in breast cancer." (PMID 36139572, 2022). "And circ-MMP11 functioned as a sponge of miR-153-3p to regulate ANLN expression, thereby promoting lapatinib resistance in breast cancer cells, providing therapeutic targets for the treatment of breast cancer." (PMID 34295807, 2021). "The molecular mechanisms and pathways of carcinogenesis according to high MMP-11 expression in breast cancer have not yet been completely explained." (PMID 34038440, 2021). "Co-expression analysis and gain- or loss-of-function of PTK7 in TNBC cell lines revealed that PTK7 participates in EGFR/Akt signaling regulation and associated with extracellular matrix organization and migration genes in breast cancer, including COL1A1, FN1, WNT5B, MMP11, MMP14 and SDC1." (PMID 34367983, 2021). "Third, the relationship between the expression of MMP-11 by the molecular subtype of breast cancer and prognosis is not analyzed." (PMID 34038440, 2021). "However, a correlation between the clinical outcomes of breast cancer and high MMP-11 expression has been reported, but little has been reported about the anti-tumor immunity role of MMP-11 expression in breast cancer." (PMID 34038440, 2021). "Also, we showed the exosomal circ-MMP11/miR-153-3p/ANLN axis in cell growth, metastasis, and chemotherapy resistance in LR-resistant breast cancer cells." (PMID 34295807, 2021). "In breast cancer, the metabolic role of MMP11 was not addressed and mechanisms behind MMP11-mediated breast tumor growth remain poorly comprehended." (PMID 32825455, 2020).
breast carcinoma (continued). "Gene expression of MMP1 and MMP11 in PBMC from breast cancer patients (n = 54) and control (n = 28); expression of IL1A, IL6, IL17, IFNβ, and NFĸB in breast cancer cell lines (MCF-7 and MDA-MB-231); and, additionally, IL10 and MMP11 in CAF and NF were analyzed by qRT-PCR before and after co-culture." (PMID 33396463, 2020). "To test this, firstly we investigated the influence of breast cancer cells on MMP1 and MMP11 gene expression by performing PBMC-breast cancer cells co-cultures (not selected on the basis of MMP11 expression)." (PMID 33396463, 2020). "A recent study further supports a potential role of MMP2 in breast-to-brain metastasis, as it was found to belong to 5-gene expression signature (together with CXCL12, MMP11, VCAM1, MME) discriminating between primary breast cancer and breast cancer brain metastases." (PMID 29312881, 2017). "In addition, it also remained conflicting as to the influence of MMP-1, MMP-2, MMP-11, MMP-13 and MMP-14 expression on the survival of breast cancer patients." (PMID 26270045, 2015). "Therefore, MMP11 and HPSE2 were selected for real-time RT-qPCR validation to investigate their potential roles as a gene set in breast cancer progression." (PMID 26084486, 2015). "It is showed that MMP-11 was expressed specifically by fibroblasts in breast carcinomas and not in their benign counterparts." (PMID 26456994, 2015). "IL-33 and sST2 were positively correlated with VEGF, MMP-11, and PDGF-C in breast cancer patients." (PMID 26456994, 2015). "Similarly, abundant MMP-11 and MMP-2 immunoreactivity in tissue from patients with breast cancer corresponded to a shorter disease-free survival and poorer overall survival." (PMID 17311017, 2007). "The results presented suggest that several mechanisms may be involved in MMP-11 and MT1-MMP regulation as part of the complex epithelial-stromal interactions that occur within human breast carcinomas." (PMID 15272933, 2004). "Thus, we investigated the induction of MT1-MMP and MMP-11 in NIH3T3 and MEFs co-cultured with a range of HBC (human breast cancer) cell lines of varied invasive and metastatic potential." (PMID 15272933, 2004). "Moreover, MT1-MMP and MMP-11 have both been reported to be induced in human fibroblasts treated with conditioned medium from MDA-MB-231, a highly invasive mammary tumour cell line." (PMID 15272933, 2004). "In addition, TAMs have been associated with increased angiogenesis in HER2+ breast cancer, and MMP11, a protein found in macrophages, has been found to play a pro-tumoral role in HER2+ breast cancer by enhancing the migration of cancer cells and recruiting monocytes." (PMID 38339385, 2024). "MMP11 expression on macrophages is an independent negative prognostic factor in breast cancer." (PMID 36591235, 2022). "In addition, our results also confirmed that the regulatory role of exo-circ-MMP11 on lapatinib resistance, cell growth, and metastasis could be mediated by the miR-153-3p/ANLN axis in LR breast cancer cells." (PMID 34295807, 2021). "Furthermore, these findings suggested that circ-MMP11 could be mediated transfer by exosomes, and circ-MMP11 could enhance the lapatinib resistance through regulating the miR-153-3p/Anillin (ANLN) in breast cancer." (PMID 34295807, 2021). "Hh pathway activation may also promote invasiveness of breast cancer cells: GLI1 enhances the invasiveness of HR negative cells by upregulating matrix metallopeptidase 11 (MMP-11)." (PMID 31394751, 2019). "Likewise, our group previously reported that tumors with MMP-11 expression by MICs showed a high cell immune ratio ((CD68+) macrophages/(CD3+) T cells + (CD20+) B cells) at the invasive front, an upregulation of inflammatory-related genes, and a poor prognosis in breast carcinomas." (PMID 33669393, 2021).